PRMT1 (protein arginine methyltransferase 1)
Diseases named in the same sentence as PRMT1 in open-access papers (continued):
Sharing a sentence is not in itself a finding about the gene and the disease.
Arrhythmia (2 papers, 2018 to 2025). Any cardiac rhythm other than the normal sinus rhythm. "The ablation or inhibition of PRMT1 will diminish the functionality of IKs, extend the action potential length, and elevate the risk of arrhythmia." (PMID 41256732, 2025).
atherosclerosis (2 papers, 2022 to 2024). A disease characterized by the build-up of fatty material and calcium deposition in the arterial wall resulting in partial or complete occlusion of the arterial lumen. "Pathogenic platelets from PRMT1-controlled immune Mks may establish and accelerate atherosclerosis progression." (PMID 36152748, 2022). "Another study was conducted about the role of PRMT1 in the pathogenesis of atherosclerosis through MHC II transactivation." (PMID 39320855, 2024).
B cell lymphoma (2 papers, 2022 to 2023). "For example, GSK3368715, a PRMT1 inhibitor has been utilised in patients with B‐cell lymphoma, whilst several antagonists targeting PRMT5 have been investigated in many clinical trials for solid tumours and non‐Hodgkin lymphoma." (PMID 35090076, 2022). "PRMT1 promotes antibody affinity maturation by favoring dark zone fate and proliferation while limiting differentiation, two functions that are co-opted by mature B cell lymphoma cells." (PMID 37310381, 2023).
B-cell chronic lymphocytic leukemia (2 papers, 2021 to 2023). "PRMT1 was highly expressed in human BCL samples, roughly correlating with their proliferation: highest in Burkitt’s lymphoma (BL) and diffuse large BCL (DLBCL), and lowest in indolent chronic lymphocytic leukemia." (PMID 37310381, 2023).
chronic kidney disease (2 papers, 2023 to 2025). Impairment of the renal function secondary to chronic kidney damage persisting for three or more months. "PRMT1 itself has been associated with chronic kidney disease in multiple studies." (PMID 41226322, 2025).
diabetic retinopathy (2 papers, 2012 to 2015). "Furthermore, AT1-R activation in the rat retina also leads to high PRMT1 and low DDAH1 expression, which is implicated in the progression of diabetic retinopathy." (PMID 22546019, 2012). "The inhibition of the expression of type I PRMTs, especially PRMT1 and PRMT4, and increased SIRT1 could be therapeutic approaches for diabetic retinopathy." (PMID 26583059, 2015). "Therefore, the inhibition of type I PRMT expression, especially PRMT1 and PRMT4, and the increase in SIRT1 expression could be therapeutic approaches for diabetic retinopathy." (PMID 26583059, 2015).
head and neck cancer (2 papers, 2021 to 2024). A primary or metastatic malignant neoplasm affecting the head and neck. "To investigate whether HPV upregulates PRMT1 during cancer progression, we analyzed available head and neck cancer data from the TCGA44." (PMID 39386465, 2024). "Finally, PRMT1 levels are further increased in HPV(+) head and neck cancers." (PMID 39386465, 2024).
hepatoblastoma (2 papers, 2020 to 2023). Hepatoblastoma (HB) is a malignant hepatic tumor and is the most common pediatric liver cancer. "Another arginine methyltransferase (PRMT1) was found to be shared between core mouse embryonic profile and C2 hepatoblastoma signature." (PMID 32517078, 2020). "After deriving cell lines from the mouse model, we map cancer dependency genes using CRISPR-Cas9 screening and identify druggable targets shared with human hepatoblastoma (e.g., CDK7, CDK9, PRMT1, PRMT5)." (PMID 37414763, 2023).
injury (2 papers, 2021 to 2023). Damage inflicted on the body as the direct or indirect result of an external force, with or without disruption of structural continuity. "Although PRMT1 was not significantly increased in the IR model, PRMT1 expression was considerably upregulated in acute liver injury and acute lung injury, strongly related to oxidative stress-induced apoptosis." (PMID 36817133, 2023).
lupus (2 papers, 2024 to 2025). "A significant upregulation of PRMT1 in CD4+ T cells and B cells from human cGVHD patients, as well as in two distinct mouse models of the disease (scleroderma‐like and lupus‐like)." (PMID 41256732, 2025).
medulloblastoma (2 papers, 2020 to 2022). A malignant, invasive embryonal neoplasm arising from the cerebellum. "The depletion of PRMT1 induced apoptosis in medulloblastoma cells, while treatment with PRMT5 inhibitor decreased tumor growth and increased survival in a SHH medulloblastoma mouse model." (PMID 36671446, 2022).
metastatic cancer (2 papers, 2016 to 2025). A carcinoma which has spread from the original site of growth to another anatomic site. "Collectively, these insights highlight opportunities to develop substrate‐selective PRMT1 inhibitors and refine preclinical models, bringing us closer to translating these findings into targeted therapies for metastatic cancer." (PMID 40884268, 2025). "Therefore, theoretically, PRMT1 can be targeted either to prevent cancer cell dissemination to develop metastatic lesions, or to eradicate existing metastatic cancer cells by induction of senescence." (PMID 26813495, 2016).
oral cancer (2 papers, 2019 to 2024). "We had conducted PRMT1 studies in HeLa cells and in an oral cancer cell line SAS31,43." (PMID 30741995, 2019). "Interestingly, PRMT1-silenced cells did not change the protein levels of FXR1 or FXR2, indicating that FXR1 may be a direct substrate of PRMT5 in oral cancer cells." (PMID 38709899, 2024).
rhabdomyosarcoma (2 papers, 2021 to 2022). A rare aggressive malignant mesenchymal neoplasm arising from skeletal muscle. "The expression of PRMT1, CARM1, PRMT5, PRMT7, PRMT8 and PRMT9 were all elevated in rhabdomyosarcoma, CARM1 and its direct interaction with histone acetyltransferase PCAF jointly were also detected to exert an increased expression of myogenin gene and lead to rhabdomyosarcoma cell differentiation." (PMID 35311114, 2022).
type 2 diabetes (2 papers, 2024 to 2025). "The mRNA and protein expression of PRMT1 exhibited significant upregulation in the kidneys of diabetic rats as well as in patients with type 2 diabetes." (PMID 39063139, 2024).
abdominal aortic aneurysm (1 paper, 2021). Enlargement and ballooning of the vessel that supplies arterial blood to the abdomen, pelvis and legs. "Consistently, Prmt1 expression was found to be reduced in the transcriptome datasets of aortas of patients with abdominal aortic aneurysms and aged aortas." (PMID 34635781, 2021).
acute kidney injury (1 paper, 2023). Sudden and sustained deterioration of the kidney function characterized by decreased glomerular filtration rate, increased serum creatinine or oliguria. "Protein arginine methyltransferase‐1 (PRMT1) is a key regulator of renal dysfunction caused by sepsis‐induced acute kidney injury (SI‐AKI)." (PMID 37525933, 2023).
acute leukemia (1 paper, 2016). A clonal (malignant) hematopoietic disorder with an acute onset, affecting the bone marrow and the peripheral blood. "Pharmacological inhibition of KDM4C/PRMT1 suppresses transcription and transformation ability of MLL fusions and MOZ-TIF2, revealing a tractable aberrant epigenetic circuitry mediated by KDM4C and PRMT1 in acute leukemia." (PMID 26766589, 2016).
alcoholic hepatitis (1 paper, 2017). Acute hepatitis resulting from ingestion of alcohol. "Reduced DDAH protein expression and increased PRMT-1 were observed in alcoholic hepatitis livers, thus indicating that the increase in ADMA may result from both the decreased breakdown and/or increased production." (PMID 27604291, 2017).
amyotrophic lateral sclerosis (1 paper, 2022). Amyotrophic lateral sclerosis (ALS) is a neurodegenerative disease characterized by progressive muscular paralysis reflecting degeneration of motor neurons in the primary motor cortex, corticospinal tracts, brainstem and spinal cord. "For instance, aggregated FUS mutants associated with amyotrophic lateral sclerosis sequester the histone methyltransferase PRMT1 to the cytoplasm, leading to a decrease in the levels of asymmetric H4R3me2." (PMID 36558770, 2022).
aortic aneurysm (1 paper, 2021). A ruptured aneurysm located in the wall of the proximal portion of the descending aorta proceeding from the arch of the aorta. "The expression of PRMT1 and contractile-related genes was significantly decreased in the aortas of elderly humans and patients with aortic aneurysms." (PMID 34635781, 2021).
Autoimmunity (1 paper, 2023). The occurrence of an immune reaction against the organism's own cells or tissues. "FOXP3 is dimethylated by PRMT5 (or PRMT1, PRMT6) at R48 and R51, which attenuates the expression of immunosuppressive genes and may lead to autoimmunity." (PMID 37143582, 2023).
benign bone tumours (1 paper, 2021). "Our data demonstrate that the proportion of cells with positive PRMT1 expression was obviously higher in OS patient samples than that in control and benign bone tumours." (PMID 34155784, 2021). "The expressions of PRMT1 were significantly up‐regulated in OS tissues compared with the adjacent normal tissues and benign bone tumours." (PMID 34155784, 2021). "Therefore, we detected the expression of PRMT1 in both conventional OS and two types of benign bone tumours, osteoid osteoma and chondroblastoma, by immunohistochemistry." (PMID 34155784, 2021). "We detected the expression of PRMT1 via immunohistochemical staining of clinical samples from three major subtypes of conventional OS (osteoblastic, chondroblastic and fibroblastic) and two types of benign bone tumours (osteoid osteoma and chondroblastoma)." (PMID 34155784, 2021).
bone tumour (1 paper, 2021). "Moreover, the mRNA levels of PRMT1 in bone tumour and control tissues were measured by qPCR." (PMID 34155784, 2021).
brain tumours (1 paper, 2021). "We discuss the relevance of PRMTs in brain tumours with a particular focus on PRMT1, -2, -5 and -8." (PMID 33404912, 2021).
Cerebral ischemia (1 paper, 2025). Restriction of arterial blood supply to the brain associated with insufficient oxygenation to support the metabolic requirements of the tissue. "Considered together, these results indicate that DICAR exerts pro-angiogenic effects on cerebral ischemia through the modulation of the miR-361-5p/PRMT1 regulatory axis, independent of direct miRNA sponging mechanisms." (PMID 41446787, 2025).
chondroblastoma (1 paper, 2021). A benign, chondroid-producing, well-circumscribed, lytic neoplasm usually arising from the epiphysis of long bones. "In addition, high expression of PRMT1 is observed in the three major subtypes of OS but not in osteoid osteoma and chondroblastoma." (PMID 34155784, 2021).
chronic obstructive pulmonary disease (1 paper, 2025). A chronic and progressive lung disorder characterized by the loss of elasticity of the bronchial tree and the air sacs, destruction of the air sacs wall, thickening of the bronchial wall, and mucous accumulation in the bronchial tree. "This study investigates the role of protein arginine methyltransferase 1 (PRMT1) in endothelial cells (ECs) in chronic obstructive pulmonary disease (COPD)." (PMID 40135804, 2025).
chronic viral hepatitis (1 paper, 2015). "Moreover, in hepatocarcinogenesis of chronic viral hepatitis protein phosphatase 2A (PP2A) and the protein arginine methyltransferase 1 (PRMT1) are both dysregulated." (PMID 25861629, 2015).
cleft palate (1 paper, 2025). Cleft palate is a fissure type embryopathy that affects the soft and hard palate to varying degrees. "This study demonstrates that PRMT1-regulated MSX1 phase separation is a key mechanism underlying cleft palate formation during craniofacial development, with MSX1 phase separation being triggered by its IDR and precisely modulated by PRMT1-mediated dimethylation of R150 and R157 in the MSX1 IDR." (PMID 40693189, 2025).
colitis (1 paper, 2026). Inflammation of the colon. "Additionally, genetic ablation of PRMT1 in myeloid cells not only impairs STAT3 activation but also exacerbates colitis and promotes inflammation-associated tumorigenesis." (PMID 42220092, 2026).
colon adenocarcinoma (1 paper, 2023). "Clinical analysis not only confirms the tumor suppressive role of RIP3 methylation and PRMT1, but also suggests that RIP3ADMA and PRMT1 can be the molecular markers for evaluating the colon adenocarcinoma malignancy." (PMID 37005412, 2023).
corneal diseases (1 paper, 2025). "Overall, our findings uncover a critical role for PRMT1 in controlling basal cell proliferation and migration to maintain corneal epithelial homeostasis, thereby providing potential therapeutic targets for the treatment of corneal diseases." (PMID 40817369, 2025). "Therefore, future studies should investigate whether PRMT1 is involved in the pathogenesis of corneal diseases by regulating corneal epithelial thickness." (PMID 40817369, 2025).
COVID-19 (1 paper, 2022). A disease caused by infection with severe acute respiratory syndrome coronavirus 2. "We speculated that immune Mks migrate to lung and cardiac tissues in large amount especially in severe COVID-19 patients and that COVID-19 platelets may be generated from immune Mks, expressing higher levels of PRMT1 in the lungs, which lead to severe thrombosis." (PMID 36152748, 2022). "Thus, it is plausible to predict that targeting PRMT1 could be used to alleviate thrombo-inflammation in patients with severe COVID-19." (PMID 36152748, 2022).
Crohn disease (1 paper, 2020). A gastrointestinal disorder characterized by chronic inflammation involving all layers of the intestinal wall, noncaseating granulomas affecting the intestinal wall and regional lymph nodes, and transmural fibrosis. "Correspondingly, the upregulation of PRMT1 and PRMT5 expression also accompanied bowel inflammation in patients with Crohn’s disease and ulcerative colitis." (PMID 32932854, 2020).
endometriosis (1 paper, 2022). The growth of functional endometrial tissue in anatomic sites outside the uterine body. "Our qPCR showed that the expression level of PRMT5, but not PRMT1 or PRMT3, was obviously decreased in the eutopic endometrium of endometriosis patients compared with that in fertile controls." (PMID 36195592, 2022).
endometritis (1 paper, 2022). An acute or chronic, usually bacterial infectious process affecting the endometrium. "Recently, some studies have reported increased expression of PRMT1 and PRMT3, two type I enzymes, in the endometrium of LPS-induced endometritis rats and the decidua of recurrent miscarriage patients, respectively." (PMID 36195592, 2022).
erythroleukemia (1 paper, 2013). Acute erythroid leukemia characterised by the presence of at least 50% erythroid precursors and at least 20% myeloblasts in the bone marrow. "The effect of PRMT1 was further examined in a different erythroleukemia cell line HEL." (PMID 23483889, 2013).
Ewing sarcoma (1 paper, 2025). A small round cell tumor that lacks morphologic, immunohistochemical, and electron microscopic evidence of neuroectodermal differentiation. "Immunoblotting across a panel of Ewing sarcoma cell lines detected PRMT1 and PRMT5 expression and associated activity." (PMID 40823091, 2025). "In this study, we identify a role for the arginine methyltransferases PRMT1 and PRMT5 in the survival of Ewing sarcoma cells." (PMID 40823091, 2025).
follicular lymphoma (1 paper, 2023). Follicular lymphoma is a form of non-Hodgkin lymphoma characterized by a proliferation of B cells whose nodular structure of follicular architecture is preserved. "We then examined the expression of PRMT1 in scRNA-seq data from three DLBCL and one transformed follicular lymphoma (tFL) clinical samples." (PMID 37310381, 2023).
gastric tumor (1 paper, 2023). "We discovered that the c-Fos protein undergoes autophagic degradation and found that PRMT1-mediated methylation at R287 protects c-Fos from autophagosomal degradation and is linked to clinicopathologic variables as well as prognosis in stomach tumor." (PMID 37564212, 2023). "Intestinal-type GC categorized by Lauren classification showed significantly higher expression of PRMT1 mRNA than diffuse-type GC, suggesting that the expression of PRMT1 is more strictly associated with well-differentiated gastric tumor types than with poorly differentiated types." (PMID 37564212, 2023). "Among autophagy genes in the Reactome database, PRMT1 was negatively correlated with genes such as ATG9A, DYNC1H1, EPAS1, PINK1, TSC1, TUBB6, and ULK1 in gastric tumor tissues (STAD-TCGA) and positively correlated with HMMR, ESCO2, CHAC2, and NUDT6 (STAD-TCGA)." (PMID 37564212, 2023). "PRMT1 expression was observed to be higher in stomach cancer tissues in GSE62254, GSE26899, GSE54129, and GSE79973 than in normal gastric tissues, normal samples in GTEx, or normal samples in TCGA, confirming that PRMT1 expression is high in patients with GC." (PMID 37564212, 2023).
heart attack (1 paper, 2022). "Cardiac-specific PRMT1 ablation induces myocardium hypertrophy and heart attack through CaMKII dysregulation, while skeletal muscle–specific Prmt1 KO leads to muscle atrophy via hyperactivated FOXO3 with enhanced energy deprivation." (PMID 35921899, 2022).
hemoglobinopathies (1 paper, 2021). "Other epigenetic enzymatic activities implicated in γ-globin repression that have potential to serve as druggable targets in hemoglobinopathies include the EHMT1/2 histone methyltransferase heterodimer and the PRMT5 and PRMT1 protein arginine methyltransferases." (PMID 34713248, 2021). "Of note, a number of PRMT small molecule inhibitors specifically targeting PRMT5 and PRMT1 have been developed and are now entering clinical trials, but not yet for treating hemoglobinopathies." (PMID 34713248, 2021).
hemorrhage (1 paper, 2025). Loss of blood from the vascular compartment to the exterior or into nonvascular body space as a result of rupture or severance of the blood vessels. "Endothelial‐specific PRMT1 knockout mice exhibit pulmonary hemorrhage, inflammation, barrier disruption, and apoptosis, accompanied by hyperactivation of nuclear factor kappa B (NF‐κB)." (PMID 40135804, 2025).
Hodgkins lymphoma (1 paper, 2012). A heterogeneous group of malignant lymphoid neoplasms of B-cell origin characterized histologically by the presence of Hodgkin and Reed-Sternberg (HRS) cells in the vast majority of cases. "We first show that the protein arginine methyltransferases, CARM1, PRMT1 and PRMT5 are strongly expressed in Hodgkin Reed-Sternberg (HRS) cells, and up-regulated in Hodgkin's lymphoma (HL) cell lines." (PMID 25436604, 2012).
hypertrophic cardiomyopathy (1 paper, 2023). A condition in which the myocardium is hypertrophied without an obvious cause. "For instance, mutation at R145 of cTnI was associated with hypertrophic cardiomyopathy due to the inhibition of PRMT1-mediated methylation on R146/R148." (PMID 37951845, 2023). "Then, to clarify the underlying signaling pathway regulated by PRMT1 in cardiac remodeling, we screened some potential signaling pathways that were relevant to cardiac contraction and hypertrophic cardiomyopathy, including p-GSK3β/GSK3β, p-ERK/ERK, p-AKT/AKT and NICD/Notch1." (PMID 37951845, 2023).
Infertility (1 paper, 2021). "Prmt1 KO mice showed infertility with approximately 70% reduction in the testis size of adult mice." (PMID 34360715, 2021).
inflammatory skin disease (1 paper, 2021). Inflammatory skin disorders covers a broad category that includes many conditions ranging in severity, from mild itching to grave medical health complications These disorders are common in people of all ages and races. "In AZ(−) conditions, THDC up-regulated genes increased as part of the unhealthy skin signature (P < 0.01), which is a set of genes increased in diverse types of inflammatory skin disease (e.g., SOD2, PRMT1, RCC1)." (PMID 34445461, 2021).